SERF2 (small EDRK-rich factor 2)
Description:
Positive regulator of amyloid protein aggregation and proteotoxicity. Induces conformational changes in amyloid proteins, such as HTT, driving them into compact formations preceding the formation of aggregates.
Synonyms: 4F5rel; h4F5rel; FAM2C; Hero7; HsT17089
Tractability: PROTAC: ubiquitination databases record sites on it; its protein half-life has been measured.
Gene: Protein-coding gene on chromosome 15 (43,777,087 to 43,804,427, forward strand). Ensembl gene ENSG00000140264.
Subcellular location (Human Protein Atlas): Nucleoplasm; Nucleoli
Gene Ontology:
Biological process: protein destabilization
Cellular component: cytosol; nucleus
Genetic constraint (gnomAD): Loss-of-function variants: 2 observed, 7.82 expected, observed/expected ratio (o/e) 0.26, 90% interval 0.1 to 0.81. That is too few expected variants to judge how well the gene tolerates losing a copy. Missense variants: 40 observed, 69.66 expected, observed/expected ratio (o/e) 0.57, 90% interval 0.44 to 0.75. Synonymous variants: 22 observed, 24.24 expected, observed/expected ratio (o/e) 0.91, 90% interval 0.65 to 1.3.
Homologues: Orthologues: zebrafish serf2b (83% identical), zebrafish serf2a (80% identical).
Diseases named in the same sentence as SERF2 in open-access papers:
SERF2 is named in the same sentence as 19 diseases in open-access papers, as found by Europe PMC text mining. Sharing a sentence is not in itself a finding about the gene and the disease. The quoted sentences say what the papers report.
ischemic stroke (3 papers, 2023 to 2025). A stroke disorder caused by obstruction of blood flow to the brain, due to thrombotic (local blood clot formation) or embolic (due to a blood clot or other material traveling from another site) event. "In our prior research, we investigated the impact of four Hero genes—C9orf16 (Hero9), SERBP1 (Hero45), SERF2 (Hero7), and C19orf53 (Hero11) —on ischemic stroke risk, finding a notable association between these genes and the disease." (PMID 39595169, 2024). "In our previous studies, we revealed an association between the risk of ischemic stroke and the genes C9orf16, C19orf53, SERBP1, and SERF2 using a population genetics-based approach." (PMID 40459864, 2025). "In order to address the involvement of Hero-proteins in the pathobiology of CVDs, we have previously conducted a genetic study exploring the associations of the genes C19orf53, SERBP1, SERF2, and C9orf16 (BBLN) with ischemic stroke." (PMID 40459864, 2025).
breast carcinoma (2 papers, 2024 to 2025). "The 1.5–3 μM concentrations of SERF2 that allow phase separation in the presence of rG4s are below the SERF2 concentrations present in human cells which range from ~7 μM in U2OS cells to ~23 μM in MCF7 breast cancer cells." (PMID 41022793, 2025).
Stroke (2 papers, 2023 to 2024). Sudden impairment of blood flow to a part of the brain due to occlusion or rupture of an artery to the brain. "In a separate study, we found that a mutation reducing the expression of Hero-7 (SERF2) is also associated with an increased risk of stroke." (PMID 39723236, 2024). "Here, providing genetic evidence that rs4644832 is associated with IS risk, we report SERF2 is involved in pathogenesis of stroke." (PMID 37252629, 2023). "However, there is no conclusive evidence linking SERF2 to the pathobiology of stroke, apart from its involvement in the atherothrombotic component." (PMID 39723236, 2024).
dyslipidemia (1 paper, 2025). "Interestingly, SERF2 rs4644823 G/A turned out to increase the risk of dyslipidemia while preventing hypertension and peripheral artery disease in smokers." (PMID 40459864, 2025).
melanoma (1 paper, 2024). A malignant, usually aggressive tumor composed of atypical, neoplastic melanocytes.
neuroblastoma (1 paper, 2018). Neuroblastoma (NB) is the most common solid, extracranial childhood tumor. "We therefore used short-hairpin RNA (shRNA) constructs to knock down SERF2 expression in a human neuroblastoma cell line expressing an aggregation-prone mutation of amyloid precursor protein (SY5Y-APPSw)." (PMID 30291272, 2018). "In SY5Y-APPSw neuroblastoma cells that form extracellular amyloid, SERF2 knockdown reduced those aggregates by 50–70%." (PMID 30291272, 2018). "A human ortholog of CRAM-1, SERF2 (also largely disordered), promotes aggregation in SH-SY5Y-APPSw human neuroblastoma cells, since SERF2 knockdown protects these cells from amyloid formation." (PMID 30291272, 2018).
Parkinson disease (1 paper, 2024). A progressive degenerative disorder of the central nervous system characterized by loss of dopamine producing neurons in the substantia nigra and the presence of Lewy bodies in the substantia nigra and locus coeruleus. "SERF family proteins including human SERF2 have shown a tendency to form fuzzy complexes with misfolded proteins such as α-Synuclein which has been linked to Parkinson’s disease." (PMID 38466543, 2024). "Human small EDRK-rich factor protein SERF2 is a cellular driver of protein amyloid formation, a process that has been linked to neurodegenerative diseases including Alzheimer’s and Parkinson’s disease." (PMID 38466543, 2024). "SERF family proteins including human SERF1a, SERF2, C. elegans MOAG-4 and yeast SERF have been shown to promote amyloid formation of proteins that have been associated with fatal neurodegenerative diseases including Alzheimer’s, Parkinson’s, and Huntington diseases." (PMID 38466543, 2024).
cancer (4 papers, 2021 to 2025). A tumor composed of atypical neoplastic, often pleomorphic cells that invade other tissues. "Querying the role of DAP5 and SERF2 in cell exhaustion, we extended our analysis to 49 publicly available scRNA-seq data from pan-cancer cohorts from the TISCH database." (PMID 38490212, 2024). "Interestingly, SERF2 exhibited a distinct prognostic pattern compared to other genes, showing a positive correlation with overall survival in the pan-cancer TCGA cohort." (PMID 41419193, 2025).
neurodegenerative disease (4 papers, 2021 to 2025). A disorder of the central nervous system characterized by gradual and progressive loss of neural tissue and neurologic function. "Our observation that SERF2’s interaction with rG4 can lead to LLPT is intriguing and suggestive of a link to the possible roles of SERF2 and rG4 in neurodegenerative diseases." (PMID 41022793, 2025). "Here we describe Serf2 knockout mice that will provide a platform for the exploration of the role of SERF2 in the aggregation of proteins involved in the pathology of neurodegenerative diseases." (PMID 33713180, 2021). "Given the known role of SERF proteins in modulating aggregation, these Serf2 KO mice provide an in vivo platform to investigate the role of SERF2 protein in the pathology of neurodegenerative diseases." (PMID 33713180, 2021).
tumor (2 papers, 2025). "Specifically, the expression of SERF2 in bulk RNA sequencing data may be influenced by immune cell infiltration or the presence of less aggressive tumor samples, which could alter its associations with clinical outcome." (PMID 41419193, 2025).
cardiovascular diseases (1 paper, 2025). "Here, we aimed to perform a bioinformatic analysis of the overall contribution of the tag SNPs of genes C11orf58 (Hero-20), C19orf53 (Hero-11), C9orf16 (Hero-9), C19orf53 (Hero-11), SERBP1 (Hero-45), and SERF2 (Hero-7), encoding the Hero-proteins to cardiovascular diseases." (PMID 40459864, 2025).
SERF2 also shares sentences with these, for which no sentence is quoted: Huntington disease (2 papers); Alzheimer disease (1); Arrhythmia (1); cervical cancer (1); Hypertension (1); metastatic tumors (1); Obesity (1); peripheral artery disease (1).